ETV1 (ETS variant transcription factor 1)
Diseases named in the same sentence as ETV1 in open-access papers (continued):
Sharing a sentence is not in itself a finding about the gene and the disease.
melanoma (continued). "Importantly, we present evidence that ETV1 suppresses motility and migration of melanoma cells and therefore function as a tumor suppressor." (PMID 26158900, 2015). "Taken together in melanoma, the role of ETV1 and its mode of regulation are still mostly unknown." (PMID 26158900, 2015). "In particular, ELK3, ETS1, ETV1, ETV4, ETV5, and SPI1 were significantly upregulated in melanoma, whereas EHF, ELF3, ELF5, ERG, ETS2, ETV7, and SPDEF were significantly downregulated in the tumor." (PMID 33424867, 2020). "In human melanoma cells, CIC represses mRNA expression of the PEA3 subfamily of ETS transcription factors, namely ETV1, ETV4 and ETV5." (PMID 26683696, 2015). "ETV1 is amplified in >40% of melanomas, and overexpression following chromosomal translocation of either ERG or Etv1 to the androgen-inducible TMPRSS2 promoter is present in most prostate tumors." (PMID 25866208, 2015). "Transcriptional outputs arising from elevated ERK activity seen in BRAF V600-mutant melanomas and KIT-mutant gastrointestinal stromal tumours (GISTs) may also be mediated through ETV1 unconstrained by COP1." (PMID 34066106, 2021). "In agreement with MMP1 reduced expression, BRD32048 inhibition of ETV1 reduces cancer cell invasion and proliferation in both LNCaP (prostatic) and 501mel (melanoma) ETV1-dependent cell lines, but not in PC3 as an ETV1-independent prostatic cell line." (PMID 29921764, 2018). "In order to rule out the possibility that the observed effects of ETV1 on motility and migration are confounded by enhanced proliferation, the ETV1- and mock-transduced melanoma cells were tested with XTT-based net-proliferation assay." (PMID 26158900, 2015). "A recent study showed a very small subset of melanomas (5.3%) that over-expresses ETV1, but the function was not directly tested." (PMID 26158900, 2015). "On the other hand, enhanced, ETV1-dependent, proliferation was also observed in a single melanoma cell line that lacked ETV1 amplification." (PMID 26158900, 2015). "Although ETV1 showed no significant prognostic relevance in melanoma in the present study, its importance in a subset of melanomas with ETV1 amplification could not be underestimated and ignored." (PMID 33424867, 2020). "Altered ETV1 expression does not affect melanoma net-proliferation." (PMID 26158900, 2015). "Indeed, a 3–4-fold decrease of ETV1 protein levels are observed following miR-17 transfection into the various melanoma lines, with no significant change in ETV1 mRNA expression." (PMID 26158900, 2015). "ETV1, the only ETS factor with ChIP-seq data in our collation of melanoma-specific functional datasets, did not have binding activity at the CDC20 promoter in the 2 cell lines assayed (A375 and COLO-800)." (PMID 38030698, 2023).
breast cancer (15 papers, 2007 to 2025). A primary or metastatic malignant neoplasm involving the breast. "Functionally, Etv1 knockdown reduced proliferation and colony formation capacity in mouse and human breast cancer cells." (PMID 40546087, 2025). "One breast cancer study indicated that cell proliferation and invasion in triple-negative breast cancer can be suppressed through miR-17-5p targeting ETV1, and ETV1 was proven to be a significant oncogene in triple-negative breast cancer." (PMID 32079071, 2020). "First of all, we observed COP1 and ETV1 expression status in several breast cancer cell lines, and found that breast cancer cell lines with relatively higher ETV1 expression displayed less COP1 abundance." (PMID 25884720, 2015). "PCa vs control comparisons revealed some startling increases of mRNA levels of: ETV1, a gene that directs androgen metabolism and confers aggressive PCa; FASN, a fatty acid metabolism gene highly up-regulated in PCa; RBM39, a gene implicated in colorectal and breast cancer progression." (PMID 28143451, 2017). "ETV5, a member of the subfamily of PEA3 (ETV1, ETV4, and ETV5), has a prominent role in regulating the progression of human breast cancer and thyroid cancer." (PMID 33931578, 2021). "ETS variant transcription factor 5 (ETV5), also called ERM, belongs to the PEA3 subfamily (ETV1, ETV4, and ETV5), was first reported to have a potential role in the regulation of breast cancer growth and progression." (PMID 33931578, 2021). "Previously, the role of ETV1 in invasiveness and metastasis has been reported in digestive cancers including GIST, colorectal, gastric, pancreatic and hepatocellular carcinoma as well as prostate and breast cancers." (PMID 40275610, 2025). "This analysis has revealed a number of intact transcripts that are massively upregulated by recurrent geneUIB fusions, including IGF2 in colorectal, ETV1 in prostate, IGF2BP3 in thyroid, and ANO3, LIPG, FUT5, and RSG9 in breast cancers (ordered by the expression fold change within a tumor type)." (PMID 32631391, 2020). "In breast cancer, HER2 interacts with ETV1 to synergistically activate the transcription of hTERT, making breast cancer more invasive; ETV1 can also coordinate with HER2/Neu to upregulate the expression of Rcl, and the combination of ETV1 and the Rcl is related with later tumor staging." (PMID 39668941, 2025).
prostate tumors (13 papers, 2010 to 2025). "The most studied association between ETV1 and malignancy pertains to prostate tumors, where ETV1 can be overexpressed due to chromosomal translocations." (PMID 36890812, 2023). "The oncogenic transcription factor ETS variant 1 (ETV1) becomes overexpressed in many prostate tumors by chromosomal translocations involving the ETV1 gene and androgen-responsive promoters or by loss of its negative regulator, the ubiquitin ligase COP15,6." (PMID 31160676, 2019). "ETV1 is overexpressed in many prostate tumors and is associated with a higher Gleason score in aggressive prostate tumors." (PMID 28039468, 2017). "Though speculative, the LTR has been implicated in an oncogenic translocation in the form of an overexpressed LTR_Hs-B-ETV1 fusion transcript in a prostate tumor of an ETV1-truncated variant." (PMID 39205286, 2024). "Furthermore, SMAD3 and SMAD4 were also downregulated in human prostate tumors being positive for ETV1 gene fusions." (PMID 31160676, 2019). "In addition, ETV1 promotes prostate tumor progression by directly inhibiting CHK1 expression." (PMID 39668941, 2025). "Most tumors, which would have been classified as ETS negative based on the exclusive assessment of the few ETS genes known to be translocated in prostate tumors (i.e., ERG, ETV1 and ETV4) had in fact significantly alterations of other ETS factors." (PMID 20479932, 2010). "Despite the consistent reports on the involvement of either ETV1 or ETV4 in invasion and AIG in vitro, and comparing to what is accepted for other tumor types, validation of the contribution of these PEA3 members to an increased aggressiveness of prostate tumors is only emerging." (PMID 25595908, 2015).
colorectal cancer (12 papers, 2019 to 2025). A primary or metastatic malignant neoplasm that affects the colon or rectum. "The CpG site cg11279021 influences the methylation of the ETV1 gene, which may play significant roles in colorectal cancer development and is significantly associated with the infiltration of cancer-associated fibroblasts and M2 macrophages." (PMID 40177272, 2025). "Likewise, ETV1 has recently been implicated in colorectal cancer development, yet the underlying mechanisms have remained unclear." (PMID 36890812, 2023). "Transcriptomic studies on human HCT116 colorectal cancer cells pointed at potential downstream effectors of ETV1, including the basic helix-loop-helix family member E40 (BHLHE40; also known as BHLHB2, DEC1, SHARP2 or STRA13)." (PMID 36890812, 2023). "Previously, we performed RNA sequencing on ETV1-depleted human HCT116 colorectal cancer cells and found downregulation of BHLHE40 mRNA." (PMID 36890812, 2023). "Previous study reported that the ERK1/2 and p38 inhibitors affect the ETV1 level in colorectal cancer cells." (PMID 36109787, 2022). "Genetic screening findings from 39 patients with colorectal cancer showed ETV1 was significantly correlated with the lymphatic metastasis of colorectal cancer." (PMID 33967600, 2021). "In another example, the ETV1 promoter is known for its interacting enhancers that affect ETV1 expression, which influences cell viability and patient survival for colorectal cancer." (PMID 32158610, 2020). "In addition, several Matrix Metalloproteinases (MMPs) such as MMP1 or MMP7, which regulate cancer invasiveness by modulating extracellular matrices degradation are regulated by high levels of ETV1 in prostate and colorectal cancers." (PMID 40275610, 2025). "Why BHLHE40 is upregulated in colorectal cancer has remained unknown, but our study strongly indicates that this could be due to enhanced activity of ETV1, JMJD1A and/or JMJD2A." (PMID 36890812, 2023). "Additional studies for GRP94/ETV1 may help to clarify the complex crosstalk between tumor cells and stroma in colorectal cancer." (PMID 33967600, 2021).
pancreatic cancer (11 papers, 2019 to 2025). "This is the first study to identify ETV1 as a transcriptional regulator of KIFC1 in pancreatic cancer cells." (PMID 40612867, 2025). "The ETV1/KIFC1 axis was involved in the abnormal expression of EMT-associated proteins and induced the proliferation, invasion, and migration of pancreatic cancer cells, thereby contributing to the progression of pancreatic cancer." (PMID 40612867, 2025). "According to a previous report, ETV1 is increased and essential for the metastatic progression of pancreatic cancer." (PMID 40612867, 2025). "In pancreatic cancer with a high ETV1 expression, the matricellular protein SPARC and the Hyaluronan Synthase 2 are two ETV1‐downstream targets responsible for its role in invasion and metastasis." (PMID 40275610, 2025). "A previous study observed increased ETV1 expression in human pancreatic cancer tissues and found that tissues with ETV1 overexpression underwent EMT and had enhanced invasive capacity." (PMID 40612867, 2025). "The present study clarified the tumor-promoting action of the KIFC1/ETV1 axis in pancreatic cancer by strengthening cell proliferation, migration, and invasion." (PMID 40612867, 2025). "In pancreatic cancer, ETV1 increases the invasive ability of pancreatic cancer cells by regulating two downstream genes Sparc and Has2." (PMID 39668941, 2025). "Similar to our finding in this study, a recent study demonstrated that Etv1 enhances Has2 expression in pancreatic cancer and alters the tumor microenvironment." (PMID 31109321, 2019). "Additionally, the KIFC1/ETV1 as novel targets to treat pancreatic cancer should be explore in clinical practice." (PMID 40612867, 2025). "In pancreatic cancer, ZBED2 acts as an antagonist of IRF1 and, along with Recombination Signal Binding Protein for Immunoglobulin Kappa J Region (RBPJ) and ETS Variant Transcription Factor 1 (ETV1), is implicated in an exhausted T-cell phenotype." (PMID 40236693, 2025). "KIFC1 serves as a tumor activator in pancreatic cancer by promoting proliferation, migration, invasion, and tumor growth, which may be partly manipulated by ETV1." (PMID 40612867, 2025). "To date, few studies have described the role of ETV1 in pancreatic cancer." (PMID 40612867, 2025). "However, copy number gain of chromosome 7p21 spanning ETV1 that was reported to promote pancreatic cancer metastasis was more frequently observed in the classical than in the basal-like." (PMID 38702773, 2024). "Indeed, a prior study suggested that overexpression of a single ETS TF confers resistance to MEKi trametinib in KRAS mutant pancreatic cancer, while suppression of ETV1, ETV4, or ETV5 alone strongly decreased the resistance." (PMID 32413516, 2020). "Moreover, ETV1 also plays a very important role in breast and pancreatic cancer." (PMID 39668941, 2025). "KIFC1 knockdown and ETV1 overexpression were used to determine the role of the ETV1/KIFC1 axis in cell proliferation, migration, invasion, and epithelial-mesenchymal transition (EMT) of pancreatic cancer cells in vitro and tumor growth in vivo." (PMID 40612867, 2025). "Collectively, it can be concluded that the ETV1/KIFC axis is crucial for the development and progression of pancreatic cancer by affecting cancer cell properties, such as proliferation, invasion, and migration." (PMID 40612867, 2025). "ETV1 overexpression reversed the role of KIFC1 knockdown in inhibiting the proliferation, invasion, migration, and EMT of pancreatic cancer cells and tumor growth in vivo." (PMID 40612867, 2025). "ETV1 induced EMT, metastasis and stromal expansion through part of the Sparc and Has2 in mice model of pancreatic cancer." (PMID 33967600, 2021).
glioma (8 papers, 2019 to 2023). A benign or malignant brain and spinal cord tumor that arises from glial cells (astrocytes, oligodendrocytes, ependymal cells). "The expression of ELK3, ETV4, and to some extent ELK4 was found to increase gradually with glioma grade, while ETV1 expression was highest in grade 2 glioma, and progressively decreased with glioma stage." (PMID 33671331, 2021). "We analyzed the expression of the major ETS-factors ETS1, GABPA, and GABPB with its splice variants, ETV1, ETV4 and ETV5 all of which were widely expressed across our glioma cell panel." (PMID 31391125, 2019). "Firstly, the endogenous expressions of PTBP1, circRNA_001160, miR-195-5p and ETV1 in astrocyte endothelial cells (AECs) and glioma endothelial cells (GECs) were detected." (PMID 31862871, 2019). "However, we have identified another PEA3 subfamily member, ETV1, to be expressed at high levels in low-grade glioma and decrease in expression in higher grades." (PMID 33671331, 2021). "Additionally, ETV1 is likely to be methylated in CIC wild-type, IDH-mutated, 1p/19q-codeleted gliomas, and fused with DGKB in pediatric high‐grade gliomas, acting as an oncogenic driver." (PMID 33470396, 2021). "Using microarray datasets from patients with different grades of glioma, we have analyzed the expression profiles of various ETS genes, and have identified ETV1, ELK3, ETV4, ELF4, and ETV6 as novel biomarkers for the identification of different glioma grades." (PMID 33671331, 2021). "PEA3 subfamily of ETS proteins (ETV1, ETV4, ETV5) amplify transcriptional signals when RAS/MAPK signaling pathway is active, and abolishing Ets activity leads to a block in glioma initiation." (PMID 31806013, 2019). "Our results demonstrated that the PTBP1/circRNA_001160/miR-195-5p/ETV1 axis was critical in the regulation of BTB permeability and provided new targets for the treatment of glioma." (PMID 31862871, 2019). "This study aimed to demonstrate the role of the PTBP1/circRNA_001160/miR-195-5p/ETV1 pathway in regulating BTB permeability, which can provide a new strategy for the comprehensive treatment for glioma." (PMID 31862871, 2019). "We show that, while ETV1 is expressed at high levels in grade 2 glioma, its expression gradually decreases with glioma stage, and on the other hand, ELK3 and ETV4 expressions are increased with progression of the glioma stage." (PMID 33671331, 2021). "The analysis of regulon activity scores showed that, while ELK-1 and ETS2 showed high regulon activity in the non-tumor condition (magenta), ETV1 showed a high activity score on mainly grade 2 glioma (green)." (PMID 33671331, 2021). "In glioma TCGA data (GBM and Lower Grade Glioma), GSEA showed that PJA1-overexpressing GBMs were enriched for oncogenic Ras signaling pathways, including the finding that high PJA1 expression correlated with high ETV1 expression." (PMID 30737375, 2019).
gastric cancer (7 papers, 2012 to 2025). A primary or metastatic malignant neoplasm involving the stomach. "Li and colleagues reported that ETV1 promotes Snail expression to induce EMT-like metastatic progression in gastric cancer." (PMID 31109321, 2019). "In gastric cancer, the level of ETV4 mRNA correlated significantly with tumor invasiveness and recurrence, while ETV1 and ETV5 expression were not related to survival." (PMID 29371979, 2017).
sarcoma (7 papers, 2012 to 2025). A usually aggressive malignant neoplasm of the soft tissue or bone. "Moreover, CIC-DUX4 sarcomas are characterised by consistent ETV1, ETV4, and ETV5 upregulation, and ETV4 immunohistochemistry has been identified as a highly sensitive marker for this tumour entity." (PMID 28680140, 2017). "No expression of ETV1 was observed in the tissues of other sarcomas." (PMID 23977394, 2013). "Recently, ETV1 transcription factor was found to be a major regulator of GIST-specific transcription networks, and it is highly expressed in GISTs but not in other sarcomas." (PMID 36778918, 2023).
lung carcinoma (6 papers, 2021 to 2025). "It was worth noting that the expression level of ETV1 in normal tissues was higher than that in lung cancer tissues; however, patients with high expression had poor prognoses." (PMID 37197420, 2023). "This phenomenon suggested two roles of ETV1 in the occurrence and development of lung cancer." (PMID 37197420, 2023). "In addition, the roles of SETDB2, SNAI3, SCML4, ZNF540, and ETV1 were validated in multiple datasets and human lung cancer cell lines." (PMID 37197420, 2023). "ZNF609 contributes to proliferation of lung cancer cells by regulating miR-1224-3p/ETV1 axis." (PMID 34520391, 2021). "To further prove the presence of enhancer activity at mouse Etv1 intron 4, we cloned the DNA fragment from the ATAC-Seq peak region into a luciferase reporter construct that was subsequently transfected into A549, a human KRAS mutant lung cancer cell line." (PMID 36810256, 2023). "To interrogate how chromatin accessibility might affect Etv1 expression in lung cancer, we assessed the ATAC-Seq tracks at the Etv1 locus, which revealed significantly increased chromatin accessibility at both promoter and intron 4 upon SETD2 loss." (PMID 36810256, 2023).
prostate adenocarcinoma (6 papers, 2015 to 2023). "In conclusion, this study has revealed a novel relationship between ETV1 and TGF-β/SMAD4, which may explain why ETV1 overexpression on its own is insufficient to cause the development of prostate adenocarcinomas." (PMID 31160676, 2019). "Using the ‘The Cancer Genome Atlas’ Prostate Adenocarcinoma (TCGA PRAD) database, significant correlations were found between high CPSF4 expression and high-risk genomic abnormalities such as ERG-fusion, ETV1-fusion, and SPOP mutations." (PMID 37629142, 2023). "The consortium published the status of ERG, ETV1, ETV4, and FLI1 fusions in the cBioportal database (dataset: Prostate Adenocarcinoma (TCGA, Cell 2015)) for 333 samples." (PMID 37349736, 2023). "In TCGA prostate adenocarcinoma samples, these fusions juxtapose the first exon of AL121790.1 with ETV1, turning ETV1 into an AR-regulated gene with high expression, as has been demonstrated in earlier studies." (PMID 30272002, 2018). "Regardless, ETV1;Pb-Cre4;Smad4f/f compound mice did not develop prostate adenocarcinomas and the degree of high-grade PIN formation was similar to ETV1 and Pb-Cre4;Smad4f/f mice." (PMID 31160676, 2019). "However, these mice were no different from ETV1 or Pb-Cre4;Smad4f/f mice and developed only high-grade PIN, but not prostate adenocarcinoma." (PMID 31160676, 2019).